FBN1 (fibrillin 1)
Diseases named in the same sentence as FBN1 in open-access papers (continued):
Sharing a sentence is not in itself a finding about the gene and the disease.
scoliosis (19 papers, 2014 to 2025). A congenital or acquired spinal deformity characterized by lateral curvature of the spine. "In light of the representation significance of DCR, we built a DCR-based deep learning classifier to predict high-risk variants for scoliosis to assess the risk potential of the FBN1 variant labelled with Pathogeniclikely or Uncertain in the ClinVar database." (PMID 39502335, 2024). "It was used to predict the scoliosis risk of variants with unclear risk and was interpreted by optimizing significant amino acids on the 3D structure of FBN1." (PMID 39502335, 2024). "The MPLS subject with a truncating FBN1 variant presented with severe scoliosis, which suggests that the protein change also alters TGF‐β signaling." (PMID 31774634, 2020). "The R2726W FBN1 variant was first described in 1995, in a 13 year old patient with tall stature, pectus carinatum, scoliosis, arachnodactyly and pes planus, leading to major involvement of the skeletal system." (PMID 26875674, 2016). "Thus, DCR of FBN1 was classifiable and predictable for high or low scoliosis risk, post convolutional transformation." (PMID 39502335, 2024). "However, the high-frequent variant distributed differently in FBN1 protein sequence, between the group of recorded Pathogenic variants (N-terminal) and the group of predicted scoliosis risk variants (C-terminal)." (PMID 39502335, 2024). "DCR-based classifier has predicted more scoliosis risk FBN1 variants in ClinVar database." (PMID 39502335, 2024). "A high association of FBN1 and the other two genes was observed with scoliosis." (PMID 39502335, 2024). "The syndrome, caused by mutations in the fibrillin-1 (FBN1, chromosome 15q) gene and dysregulation of transforming growth factor β (TGFβ), affects the skeletal system, resulting in tall stature, abnormally long and slender limbs, fingers, and toes, chest wall abnormality, and scoliosis." (PMID 37891382, 2024). "Therefore, due to the relationship between genetic variants in connective-tissue genes and scoliosis, this study was designed to investigate the association between the FBN1 rs12916536 polymorphism and the susceptibility of AIS in Brazilians, as well as its influence on the severity of the disease." (PMID 35526034, 2022). "FBN1, FBN2, and variants near SOX9, and KCNJ2 are associated with severe scoliosis (greater than 40 degrees)." (PMID 39781499, 2025). "Scoliosis was present in 74% of the children, much more than reported for classical MFS due to FBN1 variants in exon 24–32 (38%)." (PMID 40065510, 2025). "The relatively hierarchical clustering (high scoliosis risk of Pathogenic vs. Benign and Benignlikely) was also indicated by DCR of FBN1." (PMID 39502335, 2024). "FBN1 is richly distributed in structural elements of elastic and non-elastic tissues, responsible for connective tissue disorders, such as scoliosis." (PMID 35526034, 2022). "Therefore, the DCR embedding of FBN1 and the trained CNN classifier worked well in predicting scoliosis-risk variants, based on the interpretability of the high similarity in variant between pathogenic variants and predicted variants." (PMID 39502335, 2024). "Taken together, the DCR-based CNN predictor for scoliosis-risk prediction was not dependent on the protein sequence or protein structure of FBN1." (PMID 39502335, 2024). "Some porcine somatic cells have been modified by ZFNs to generate a cloned pig with a heterozygous FBN1 mutant (+/Glu433AsnfsX98), which exhibited phenotypes (scoliosis, pectus excavatum, and structural damage in the aortic medial tissue) similar to those of patients with MFS." (PMID 35845351, 2022). "However, the incidence of scoliosis in FBN1 mutant pigs studied here was lower than that in patients with MFS, and the spinal deformation was less severe." (PMID 27074716, 2016). "Therefore, this difference likely resulted in the lower incidence and reduced severity of scoliosis in the FBN1 mutant pigs." (PMID 27074716, 2016).
scoliosis (continued). "Two siblings presented with isolated skeletal manifestations of MFS, including severe pectus excavatum, elongated face, scoliosis in one case, and absence of other clinical features according to Ghent criteria diagnosis, were screened for detection of variants in whole FBN1 gene (65 exons)." (PMID 26875674, 2016). "Counting of scoliosis-related genes indicated that NF1, FBN1, LAMA2 and SPG11 led the top list of genes concerned with scoliosis." (PMID 39502335, 2024). "However, since FBN1 polymorphisms had been associated with tall stature, and isolated scoliosis in non-Marfan patients, clinical variability may be implied by allelic variants in FBN1 expression or by certain FBN1 polymorphisms." (PMID 26875674, 2016). "The FBN1 mutant pigs exhibited phenotypes resembling those of humans with MFS, such as scoliosis, pectus excavatum, delayed mineralization of the epiphysis and disrupted structure of elastic fibres of the aortic medial tissue." (PMID 27074716, 2016). "Rare mutations in FBN1 and FBN2 were associated with scoliosis, even though these scoliosis patients do not have typical features consistent with the syndromic condition." (PMID 34356049, 2021). "FBN1 is well known as a causal gene for MFS, which often has scoliosis without structural changes of the vertebrae and ribs." (PMID 31827250, 2020). "However, such clustering was not significantly binary on the raw DCR data of FBN1, implying an incapability of the raw DCR data for a binary classification for the two scoliosis risk types and a need of feature optimization of DCR by deep learning." (PMID 39502335, 2024).
gastric cancer (18 papers, 2020 to 2025). A primary or metastatic malignant neoplasm involving the stomach. "FBN1 deposition and accumulation chronically with high succinylation in gastric cancer promotes tumor development through the activation of TGF-β1 and intracellular PI3K/Akt pathways, leading to a poor prognosis." (PMID 40865948, 2025). "For example, K672/K799 succinylation of FBN1 protein in gastric cancer can inhibit ECM degradation mediated by MMP2-2 and promote tumor cell invasion." (PMID 40865948, 2025). "In gastric cancer, succinylation modification of FBN1 leads to its accumulation, activates TGF-β1 and triggers the activation of the phosphoinositide 3-kinase (PI3K)/AKT signaling, thereby promoting tumor proliferation." (PMID 38269088, 2023). "Because FBN1 is a direct target of miR-133b, downregulation of miR-133b in gastric cancer leads to the upregulation of FBN1 expression, which promotes the proliferation, migration and invasive ability of gastric cancer cells." (PMID 38269088, 2023). "Fibrillin-1 (FBN1) promotes gastric cancer progression by activating TGF-β1 and PI3K/Akt pathways, and is targeted by miR-486-5p to inhibit the growth of thyroid cancer cells." (PMID 38283355, 2023). "FBN1 gene involvement in the pathways of platelet activation was discovered in a recent work focused on a multilayer systems biology investigation of gastric cancer." (PMID 36453946, 2022). "Previous studies in gastric cancer cells have shown that miR-133b can inhibit cell proliferation, migration, and invasion by increasing the expression of FBN1." (PMID 34692659, 2021). "miR-133b inhibits the proliferation, migration, and invasion of gastric cancer cells by increasing FBN1 expression." (PMID 32934754, 2020). "In summary, we uncovered the prognostic value of COL3A1/FBN1/COL5A2/SPARC-mir-29a-3p-H19 ceRNA network in gastric cancer." (PMID 32742441, 2020). "The silencing of FBN1 inhibits the proliferative, migratory, and invasive activities of gastric cancer cells, whereas upregulation of the expression of FBN1 has the opposite effect (Yang, Zhao & Chen, 2017)." (PMID 33282565, 2020). "FBN1 is closely related to the PI3K/Akt signaling pathway in gastric cancer (GC)." (PMID 40865948, 2025). "High expression of fibrinogen 1 (FBN1), a major component of extracellular matrix (ECM), predicts poor prognosis in patients with gastric cancer." (PMID 37777749, 2023). "Of note, recent reports have underscored the pivotal roles of these genes in tumorigenesis, invasion, and prognosis (e.g., COL12A1 in gastric cancer, FAT1, and FBN1/2 in HCC)." (PMID 36900398, 2023). "In summary, FBN1, FN1, HGF, MMP9, THBS1, and VCAN can be used as new target genes to observe the prognosis of gastric cancer." (PMID 33014013, 2020). "Wang and team discovered that succinylation of fibrillin 1 (FBN1) promoted the long-term accumulation and deposition of FBN1 and activated the intracellular PI3K/Akt signaling pathway, contributing to the progression of gastric cancer." (PMID 39781339, 2025). "These included genes such as SCUBE3, MARCKSL1 and PGK1 in lung cancer, SOX4 and GNAS in breast cancer and hepatocellular carcinoma, HEG1 in hepatocellular carcinoma, PLS3 in pancreatic adenocarcinoma, FBN1 and SPARC in gastric cancer and CST1 in gastric cancer and breast cancer." (PMID 40430098, 2025). "The results showed that 8 up-regulated genes (FN1, COL3A1, FBN1, BGN, COL5A2, THBS2, COL5A1 and SPARC) and 1 down-regulated gene (ATP4A) may be the central genes in gastric cancer." (PMID 32742441, 2020). "In addition to promoting the proliferation of gastric cancer cells by activating TGF-β1 and PI3K/Akt pathways, the accumulated FBN1 can also promote the overexpression of MMP2 by increasing the level of HIF-1α, leading to extracellular matrix protein degradation and tumor metastasis." (PMID 37777749, 2023).
geleophysic dysplasia (18 papers, 2012 to 2026). Geleophysic dysplasia is a rare skeletal dysplasia characterized by short stature, prominent abnormalities in hands and feet, and a characteristic facial appearance (described as "happy''). "FBN1 gene mutation-associated geleophysic dysplasia (GD) leads to the formation of complex and refractory pulmonary hypertension (PH) through a multifactorial combination of precapillary factors, postcapillary factors, and respiratory pathology." (PMID 40740820, 2025). "Acromelic dysplasia caused by FBN1 mutation includes acromicric dysplasia (AD), geleophysic dysplasia 2 (GD2), and Weill-Marchesani syndrome 2 (WMS2)." (PMID 39077065, 2024). "Recently, 16 novel heterozygous mutations in FBN1 causing geleophysic dysplasia or acromicric dysplasia were also identified in the fifth 8-cysteine domain." (PMID 22242013, 2012). "However, FBN1 mutations in these two exons might also cause another two short‐stature syndromes, termed geleophysic dysplasia (GD) and Weill–Marchesani syndrome (WMS)." (PMID 32406602, 2020). "Acromelic dysplasia caused by fibrillin 1 (FBN1) gene mutation is an autosomal dominant disorder, consisting of acromicric dysplasia (AD, OMIM #102370), geleophysic dysplasia 2 (GD2, OMIM #614185), and Weill-Marchesani syndrome 2 (WMS2, OMIM #608328)." (PMID 39077065, 2024). "Disease-causing mutations of FBN1 disrupting heparin binding by TB5 can result in Weill–Marchesani syndrome (WMS) or Acromicric (AD) and Geleophysic Dysplasias (GD)." (PMID 37239376, 2023). "On the other hand, FBN1 mutations also cause various skeletal dysplasia, including Acromicric dysplasia (MIM #102370), Geleophysic dysplasia 2 (MIM #614185), Marfan lipodystrophy syndrome (MIM #616914), and Weill–Marchesani syndrome 2 (MIM #608328)." (PMID 31827250, 2020). "Geleophysic dysplasia (GD) is caused by recessive mutations in ADAMTSL2 (a disintegrin and metalloprotease with thrombospondin type I motifs-2; GD1), or dominant mutations in FBN1 (GD2) or LTBP3 (GD3)." (PMID 41864337, 2026). "Previously, using a similar assay, we demonstrated MFS-associated substitutions in domains TB4 and TB5 of FBN1 resulted in intracellular retention of the mutant molecules whilst apparently similar mutations associated with SSS, acromicric dysplasia and geleophysic dysplasia secreted normally." (PMID 33735269, 2021).
mitral valve prolapse (18 papers, 2010 to 2025). A fairly common and often benign valvular heart disorder characterized by redundancy or hooding of mitral valve leaflets so that they prolapse into the left atrium, often causing mitral regurgitation. "In this GD patient, the coexistence of mitral valve disease and systemic connective tissue abnormalities resulting from FBN1 mutations may exert synergistic effects that culminate in severe and refractory PH." (PMID 40740820, 2025). "The mitral valve prolapse appeared to be significantly influenced by both pathogenic and VUS rare variants in FBN1 and by NOTCH1 and TGFBR2 VUS." (PMID 31536524, 2019). "In addition, NOTCH1, Fibrillin-1 (FBN1), and Filamin (AFLNA) gene mutations have been associated with the development of degenerative calcification and mitral valve prolapse." (PMID 38739622, 2024). "Mutations in a variety of genes that are responsible for encoding structural proteins, signaling molecules, and transcription factors—namely FBN1, FLNA, MMP2, and SOX9—have been identified as significant contributors to the pathology of mitral valve diseases." (PMID 39273357, 2024).
myopia (18 papers, 2010 to 2025). "P49 also carried a novel likely pathogenic heterozygous variant p.Pro2002Arg in the FBN1 gene, which likely accounts for her ophthalmological features (OU mild myopia, OS peripheral vitreochorioretinal dystrophy)." (PMID 41393291, 2025). "–17 Furthermore, common genetic variants in these two genes have also been associated with myopia and refractive error in genome-wide association studies studies, that is, an exonic variant in PRSS56 (rs1550094-A, direction hyperopia) and an intronic variant in FBN1 (rs34539187-C, direction myopia)." (PMID 35285860, 2022). "Our cohort largely concurred with these findings and highlights vitreoretinopathies (e.g., COL2A1, FBN1) as significant contributors to syndromic myopia parallel to photoreceptor and synaptic dystrophies." (PMID 41465105, 2025). "The phenotypic subset associated with myopia (n = 130) was found to represent a set of 119 unique genes since 7 genes (COL2A1, COL11A1, FBN1, LTBP2, POMT1, POMT2, POMGNT1) had two or more associated phenotypes, leading to 11 duplicates." (PMID 29346494, 2018). "Using data from a large multi-ethnic population, our results support the role of FBN1 in myopia development." (PMID 27020472, 2016). "This novel variant may specifically promote axial elongation through scleral thinning, providing new evidence for the genetic heterogeneity of FBN1 in high myopia." (PMID 41259386, 2025). "In summary, we examined using a DNA pooling approach tag SNPs from four candidate genes (COL11A1, COL18A1, FBN1, and PLOD1) selected because pathogenic mutations in these genes cause disease syndromes that have myopia, usually high myopia, as one of the common presenting clinical features." (PMID 21527992, 2011). "In conclusion, common polymorphisms in these four candidate genes (COL11A1, COL18A1, FBN1, and PLOD1) were unlikely to play important roles in the genetic susceptibility to high myopia." (PMID 21527992, 2011).
colorectal cancer (15 papers, 2011 to 2023). A primary or metastatic malignant neoplasm that affects the colon or rectum. "Mutations of FBN1 within the pancancer cohort of TCGA cancers appear to be most frequent in melanoma, uterine, stomach and colorectal cancer." (PMID 34386072, 2021). "The detection of hypermethylated FBN1 in stool samples is a non-invasive and useful method for screening colorectal cancer." (PMID 38269088, 2023). "FBN1 is closely related to colorectal cancer, and studies suggest that FBN1 methylation is an important biomarker for monitoring colorectal cancer progression." (PMID 38269088, 2023). "In our previous research, we found that the DNA methylation rate of four molecular markers SNCA, SPG20, FBN1 and septin-9 had significant differences when colorectal cancer, colorectal adenoma and normal mucosa were compared." (PMID 33613751, 2021). "Our study showed that SNCA, SPG20, Septin9, and FBN1 can be used for colorectal cancer screening 11-12." (PMID 33613751, 2021). "High expression of fibrillin-1 has previously been reported in ES cell lines and to promote tumorigenesis and metastasis in some cancers, including ovarian and colorectal cancer." (PMID 34403115, 2021). "Prior studies have revealed that the FBN1 gene promoter was hypermethylated in colorectal cancer and endothelial tumor cells." (PMID 32984335, 2020). "The fibrillin-1 promoter has been reported to be hypermethylated in colorectal cancer cell lines, colorectal cancer patient samples and endothelial tumor cells." (PMID 28067804, 2017). "PGM5-AS1 (ENSG00000224958) is downregulated in both EOC patients and EOC cell lines; it is also downregulated and negatively correlated with oxaliplatin resistance in colorectal cancer but, on the other hand, it is upregulated and sponges miR-140-5p to prevent FBN1 mRNA degradation in osteosarcoma." (PMID 37445988, 2023). "In addition, the identification of hypermethylated FBN1 in stool samples has been used to detect colorectal cancer." (PMID 29215599, 2017). "We concluded that methylation testing of SNCA and FBN1 genes in stool sample may offer a good alternative in a simple, promising, and noninvasive detection of colorectal cancer." (PMID 25802477, 2015). "CNRIP1, FBN1, INA, MAL, and SNCA promoter methylation was analyzed quantitatively (qMSP) in the colorectal cancer (n = 74; median age 71 years) and normal mucosa (n = 51; median age 55 years) test sets." (PMID 21777459, 2011). "Methylation in colorectal cancers ranged from 55% (C3orf14) to 96% (BEX1; median 84%), while methylation in normal tissue was between 0% (CNRIP1, FBN1, INA) and 45% (BEX1; median 5%), P < 0.0001 to P < 0.02." (PMID 21777459, 2011). "Promoter hypermethylation of the genes CNRIP1, FBN1, INA, MAL, SNCA, and SPG20 was frequent in both colorectal cancers (65-94%) and adenomas (35-91%), whereas normal mucosa samples were rarely (0-5%) methylated." (PMID 21777459, 2011). "Co-methylation, here defined as simultaneous hypermethylation of two or more of the six gene promoters (CNRIP1, FBN1, INA, MAL, SNCA, and SPG20), was found in 99% of the colorectal cancer test set samples and 2% of the normal mucosa samples." (PMID 21777459, 2011). "Fibrillin-1 (FBN1) methylation risk from control to colorectal cancer (CRC), the variation regularities of FBN1 methylation, and DNA methyltransferase (DNMT) catalyzed with FBN1 methylation had not been reported yet; these were all studied in this paper." (PMID 35515111, 2022). "Moreover, hypermethylated FBN1 is found in tissue samples from colorectal cancer patients but not in healthy controls, suggesting that hypermethylated FBN1 may be a sensitive biomarker for this disease." (PMID 32934754, 2020).